GDF15 (growth differentiation factor 15)
Diseases named in the same sentence as GDF15 in open-access papers (continued):
Sharing a sentence is not in itself a finding about the gene and the disease.
thyroid nodule (2 papers, 2017 to 2023). A small circumscribed mass in the THYROID GLAND that can be of neoplastic growth or non-neoplastic abnormality. "We further divided the subjects into two groups according to age at 60 years old, and we found that GDF-15 was independently associated with thyroid nodule in patients over 60 years (P<0.01)." (PMID 28489602, 2017). "Our findings confirmed this, we found serum GDF-15 levels were independently associated with thyroid nodule in diabetic patients over 60 years." (PMID 28489602, 2017). "The major new finding of the present study is that serum GDF-15 level is positively associated with thyroid nodule in type 2 diabetic patients aged over 60 years." (PMID 28489602, 2017). "Multivariate logistic regression analysis showed that serum growth differentiation factor 15 levels were independently associated with thyroid nodule in diabetic patients over 60 years (P <0.001)." (PMID 28489602, 2017). "Since GDF-15 is correlated with age, and multiple logistic regression analysis indicated that age was independently associated with thyroid nodule (P<0.001)." (PMID 28489602, 2017). "Measurement of serum GDF-15 could be useful for thyroid nodule risk stratification in the diabetic population." (PMID 28489602, 2017). "Our findings suggest that serum GDF-15 may be involved in the higher thyroid nodule risk observed in elderly type 2 diabetic subjects." (PMID 28489602, 2017). "Only two studies in the literature have evaluated the role of GDF-15 in distinguishing benign and malignant follicular-patterned thyroid nodules." (PMID 37905271, 2023). "In the highest GDF-15 quartile, the adjusted ORs for thyroid nodule was 2.63 (95% CI, 1.30 to 5.13) after adjusting for gender, FT3, FT4, and thyroid volume." (PMID 28489602, 2017). "As assumed, we found increased ORs for thyroid nodule from the 1st to the 4th GDF-15 quartiles (P< 0.01 for trend)." (PMID 28489602, 2017). "In conclusion, serum growth differentiation factor 15 is increased significantly in subjects with thyroid nodules in type 2 diabetic patients aged over 60 years." (PMID 28489602, 2017). "As far as we know, this is the first study to link GDF-15 and thyroid nodule." (PMID 28489602, 2017). "Serum growth differentiation factor 15, thyroid function, thyroid autoantibodies, thyroglobulin and other biochemical indicators were measured and compared between thyroid nodule positive and negative groups." (PMID 28489602, 2017). "We found that overall, serum growth differentiation factor 15 levels were significantly higher in subjects with thyroid nodules compared with nodule negative subjects (181.76±98.49 pg/ml vs. 162.32±83.63 pg/ml, p<0.05), and this was influenced by age." (PMID 28489602, 2017). "The serum GDF-15 levels were significantly higher in subjects with thyroid nodules compared with nodule negative subjects (181.76±98.49 pg/ml vs. 162.32±83.63 pg/ml, p<0.05)." (PMID 28489602, 2017). "In patients under 60 years old, GDF-15 was not related to thyroid nodule." (PMID 28489602, 2017).
type 2 diabetic nephropathy (2 papers, 2015 to 2020). "Plasma GDF-15 levels were also increased with the mogensen stage in type 2 diabetic nephropathy, and, thus, it is an independent risk factor for increased microalbuminuria (mAlb)." (PMID 26273671, 2015). "It is significantly correlated with mAlb and eGFR, and thus GDF-15 would be useful in early diagnosis, evaluation, and prediction of the outcomes of type 2 diabetic nephropathy." (PMID 26273671, 2015).
ulcerative colitis (2 papers, 2023 to 2024). An inflammatory bowel disease involving the mucosal surface of the large intestine and rectum. "Animals with the dextran sodium sulfate (DSS)-induced ulcerative colitis displayed pathological outcomes in the kidney, including elevated BUN levels and tubular dilation, which were notable Gdf15 KO animals." (PMID 37270567, 2023).
Ventricular arrhythmia (2 papers, 2018 to 2025). "We compared the prognostic value of GDF‐15 and sST2 for prediction of fatal ventricular arrhythmias and all‐cause mortality in patients with non‐ischaemic DCM." (PMID 29397580, 2018).
vitamin D deficiency (2 papers, 2021 to 2022). A nutritional condition produced by a deficiency of VITAMIN D in the diet, insufficient production of vitamin D in the skin, inadequate absorption of vitamin D from the diet, or abnormal conversion of vitamin D to its bioactive metabolites. "Overall, GDF‐15 expression was lower in AA benign prostate compared with benign prostate of white men which is consistent with the known effect of Vitamin D to upregulate GDF‐15,30 along with the tendency of AA men to have a relative Vitamin D deficiency." (PMID 33784024, 2021).
abnormal glucose tolerance (1 paper, 2025). "In the stratified analyses,the negative associations between GDF15 and LTL were more prominent in subjects of women, overweight or with abnormal glucose tolerance, but similar results were observed in younger and older subjects." (PMID 39904253, 2025). "After adjusting for confounding factors, we found a significant negative linear association between GDF15 and LTL, which was more prominent in women, overweight individuals, or subjects with abnormal glucose tolerance (AGT)." (PMID 39904253, 2025).
abortion (1 paper, 2023). the ending of pregnancy by removing a fetus or embryo before it can survive outside the uterus. "To explore the potential beneficial effects of supplementation with GDF15 on early pregnancy maintenance in vivo, we examined the impacts of GDF15 supplementation in a classic LPS‐induced abortion mouse model." (PMID 37272232, 2023). "We found that supplementation with rmGDF15 protein decreased the embryo resorption rate in LPS‐induced abortion model mice, showing that GDF15 can exert a protective roles in pregnancy maintenance under specific adverse conditions." (PMID 37272232, 2023). "GDF15 supplementation of LPS‐induced abortion model mice increased circulating GDF15 level (n = 10/group) and GDF15 mRNA and protein levels in murine placentas (n = 3/group)." (PMID 37272232, 2023). "Serum GDF15 levels increase with gestational age, but decrease markedly when abortion occurs." (PMID 37272232, 2023). "In addition, GDF15 could serve as a pro‐invasive factor in human extravillous trophoblasts and upregulate JAG1/NOTCH3/HES1 pathway activity as well as rescue the embryo absorption phenotype observed in the LPS‐induced abortion mouse model." (PMID 37272232, 2023).
acne (1 paper, 2020). An inflammatory process of the sebaceous glands which is characterized by comedones, nodules, papules and/or pustules on the skin. "Based on microarray datasets GSE10432, GSE10433, and GSE11792, upregulated expression of LCN2, PTGES, and GDF15 might mediate sebocytes apoptosis; CCL2 and S100A7 could be related with “acne-flare” using isotretinoin for 1 week." (PMID 32685503, 2020). "Using isotretinoin for 1 week, LCN2, PTGES, and GDF15 were upregulated and might mediate sebocytes apoptosis and thus decreased sebum production; CCL2 originated from activated TNF signaling pathway and S100A7 could be related with “acne-flare”." (PMID 32685503, 2020). "In conclusion, this study exhibits that the upregulated expression of LCN2, PTGES, and GDF15 might mediate sebocytes apoptosis and thus decreased sebum production; while CCL2 originated from activated TNF signaling pathway and S100A7 could be related with “acne-flare” using isotretinoin for 1 week." (PMID 32685503, 2020).
acral melanoma (1 paper, 2026). "GDF-15 is shown here to be mechanically induced by ECM rigidity and compressive forces occurring during metastatic progression, leading to significantly elevated levels in both cutaneous and acral melanoma cells." (PMID 41648434, 2026).
acute cholangitis (1 paper, 2022). Cholangitis that is both sudden in onset and of a relatively short duration. "A case-control study observed a higher level of GDF-15 in patients with benign biliary diseases (acute cholecystitis, acute cholangitis, choledocholithiasis, and cholelithiasis), suggesting GDF-15 to be a potential biomarker in biliary diseases." (PMID 35769993, 2022).
alcoholic liver cirrhosis (1 paper, 2017). A disorder of the liver characterized by the presence of fibrotic scar tissue instead of healthy liver tissue. "The aim of this study was to determine the relationship between the concentration of selenium and pro-inflammatory and profibrotic cytokines—interleukin-6 (IL-6) and growth differentiation factor 15 (GDF-15) in patients with alcoholic liver cirrhosis." (PMID 28430124, 2017). "The aim of this study was to determine the relationships between the concentration of selenium and pro-inflammatory and profibrotic cytokines—interleukin-6 (IL-6) and growth differentiation factor 15 (GDF-15)—in patients with alcoholic liver cirrhosis." (PMID 28430124, 2017). "In our study, elevated levels of GDF-15 were observed in patients with alcoholic cirrhosis compared to healthy subjects." (PMID 28430124, 2017).
alopecia areata (1 paper, 2021). Loss of scalp and body hair involving microscopically inflammatory patchy areas. "In our study, the serum concentration of GDF15 correlated with the age at the onset of alopecia areata." (PMID 34830700, 2021). "A positive correlation was found between the serum concentration of CCL7 and the severity of alopecia areata (r = 0.281, p = 0.03), while GDF15 correlated with age at the disease onset (r = 0.509, p < 0.0001)." (PMID 34830700, 2021).
ameloblastoma (1 paper, 2020). The most common odontogenic tumor, arising from the epithelial component of the embryonic tooth and usually affecting the molar-ramus region of the mandible or maxilla. "We also found that expression levels of TGF‐β family genes, including TGFB1, TGFB3, and GDF15, significantly increased in ameloblastoma." (PMID 32096304, 2020).
Aortic dissection (1 paper, 2021). Aortic dissection refers to a tear in the intimal layer of the aorta causing a separation between the intima and the medial layers of the aorta. "However, the mechanism of GDF15 in the occurrence and development of aortic dissection needs to be confirmed in further research." (PMID 34277731, 2021).
Arthritis (1 paper, 2021). Inflammation of a joint. "Considering that previous studies have shown the involvement of GDF-15 in arthritis in both humans and rodents, we also examined the effect of GDF-15 on CFA-induced arthritic pain." (PMID 34076854, 2021).
Ascites (1 paper, 2025). Accumulation of fluid in the peritoneal cavity (between the layers of the peritoneum that lines the abdomen). "This may have been a consequence of ascites accumulation or a pharmacologic effect of AZD8853, as GDF15 is known to affect metabolic activity, although no consistent effects on body weight were seen in the overall patient population." (PMID 40354065, 2025).
autism (1 paper, 2024). Persistent deficits in social interaction and communication and interaction as well as a markedly restricted repertoire of activity and interest as well as repetitive patterns of behavior. "In autism models induced by PPA, GDF-15 levels rise in response to inflammation and oxidative stress in the brain, serving a regulatory function." (PMID 39329976, 2024).
Autoimmunity (1 paper, 2015). The occurrence of an immune reaction against the organism's own cells or tissues. "Therefore, the interaction among autoimmunity, admixture population, and genetic, epigenetic, and environmental factors could influence the behavior of GDF15(MIC1) in our study." (PMID 26090487, 2015).
autonomic dysfunction (1 paper, 2021). "Our findings might reflect that GDF15 expression is compensatory for autonomic dysfunction in patients." (PMID 33567936, 2021).
benign ovarian tumors (1 paper, 2018). "A few publications have demonstrated the performance of serum GDF15 in distinguishing malignant and benign ovarian tumors." (PMID 29580231, 2018).
carbohydrate metabolism disorders (1 paper, 2024). "Elevated levels of GDF-15 and the presence of mitochondrial dysfunction may be a consequence of carbohydrate metabolism disorders in patients and may be predictive of accelerated aging." (PMID 39456699, 2024). "In summary, elevated levels of GDF-15 and the presence of mitochondrial DNA deletions may be a consequence of carbohydrate metabolism disorders in patients and thus a predictor of the process of accelerated aging." (PMID 39456699, 2024). "Therefore, based on our study, we conclude that elevated levels of GDF-15 and the presence of mitochondrial dysfunction may be a consequence of carbohydrate metabolism disorders in patients and may predict accelerated aging." (PMID 39456699, 2024).
carotid atherosclerosis (1 paper, 2024). A thickening and loss of elasticity of the walls of carotid arteries that occur with formation of atherosclerotic plaques. "In elderly populations and among patients with heart disease and carotid atherosclerosis, GDF-15 levels are related to circulating markers of inflammatory activity as CRP." (PMID 39780955, 2024).
cerebral lesions (1 paper, 2019). "However, it has been shown that cryogenic cerebral lesions induced GDF-15 expression in macrophages, neurons and microglial cells." (PMID 31258506, 2019).
cervical tumor (1 paper, 2020). "GDF15 expression was accumulated in cervical tumor tissues, especially in ICC tissues, compared with NCs." (PMID 33098235, 2020).
childhood cancer (1 paper, 2023). "To begin closing the knowledge gap around GDF15 in childhood cancer, we examined serum GDF15 concentrations in children newly diagnosed with cancer compared to a control group of children without cancer." (PMID 38146512, 2023). "Despite inflammatory markers such as GDF15 coming under intense interest as potential mediators of cancer progression and cachexia, very little information exists on the role of GDF15 in pediatric cancer." (PMID 38146512, 2023). "This study represents a novel investigation into GDF15 levels in childhood cancer." (PMID 38146512, 2023).
chronic GVHD (1 paper, 2023). "In this context, we used immunoenzymatic methods to measure suPAR and GDF-15 levels in HSCT-TMA, acute and/or chronic GVHD, control HSCT recipients, and apparently healthy individuals of similar age and gender." (PMID 38203404, 2023).
chronic rhinosinusitis (1 paper, 2025). Chronic form of sinusitis. "Patient #6 (chronic rhinosinusitis), who achieved clinical improvement, showed a profile of immune resolution characterized by concurrent downregulation of GDF15 and DEFB1, signaling a return to homeostasis." (PMID 41516055, 2025).
co-infection (1 paper, 2021). "Finally, we also analyzed the levels of GDF15 in patients with different pathogens (Gram-positive bacteria, Gram-negative bacteria, fungus, virus, co-infection and undefined)." (PMID 34566964, 2021).
Cockayne syndrome (1 paper, 2025). A multisystem condition characterized by short stature, a characteristic facial appearance, premature aging, photosensitivity, progressive neurological dysfunction, and intellectual deficit. "It is established that complex I dysfunction within the liver seen in e.g., Cockayne syndrome, gives rise to high concentrations of circulating GDF15 and FGF21 resulting in suppressed food intake, which is reversed by blocking GDF15 alone." (PMID 40562759, 2025).
colitis (1 paper, 2023). Inflammation of the colon. "Therefore, Gdf15 KO also induced severe loss of the mucosal layer in the DSS-induced colitis model." (PMID 37270567, 2023). "In addition to tubular distress, we found that Gdf15 deficiency increased glomerular injuries, including morphological shrinkage and neutrophil infiltration in the DSS-induced colitis model." (PMID 37270567, 2023).
cyst (1 paper, 2023). A sac-like closed membranous structure that may be empty or contain fluid or amorphous material. "In addition, CP-induced cyst formation was notable in Gdf15 KO mice when compared with that in wild-type mice." (PMID 37270567, 2023).
cytomegalovirus infection (1 paper, 2018). A herpesvirus infection caused by Cytomegalovirus. "NT, S1P, GDF-15 and CMV infection have almost identical properties and functions." (PMID 29467963, 2018).
decreased renal function (1 paper, 2020). "In our study cohort, plasma concentrations of GDF-15, H-FABP, IGF-BP2, and suPAR were markedly elevated in patients with decreased renal function, with a 2.0- to 4.4-fold increase in biomarker levels in the advanced stages of CKD (eGFR < 30 mL/min/1.73 m2 BSA)." (PMID 32213894, 2020).
delirium (1 paper, 2021). A disorder characterized by confusion; inattentiveness; disorientation; illusions; hallucinations; agitation; and in some instances autonomic nervous system overactivity. "Finally, rates of delirium were significantly associated with raised GDF-15 levels (median 718 versus 1491 pg/ml, p = 0.0006)." (PMID 34221186, 2021).
Down syndrome (1 paper, 2024). "The value of GDF-15 as a marker of biological age was further supported by a recent study that reported that GDF-15 is expressed to a greater extent in more rapidly aging subjects, such as Down’s syndrome patients, than in their siblings of similar age." (PMID 39456699, 2024).
Duchenne muscular dystrophy (1 paper, 2022). Duchenne muscular dystrophy (DMD) is a neuromuscular disease characterized by rapidly progressive muscle weakness and wasting due to degeneration of skeletal, smooth and cardiac muscle. "Therefore, it will be of great importance to determine if GDF-15 is also a regulator of muscle regeneration in Duchenne muscular dystrophy or other types of myopathies, which are most of the time associated with the permanent presence of inflammatory cells, and especially MFs." (PMID 34846534, 2022).
End Stage Liver Disease (1 paper, 2020). Final stage of a liver disease when the liver failure is irreversible and LIVER TRANSPLANTATION is needed. "Moreover, circulating GDF15 levels strongly correlated with the Mayo risk score (r = 0.685, p = 0.0009) and Model for End-stage Liver Disease score (r = 0.687, p = 0.0008)." (PMID 33178828, 2020).
energy metabolic disorder (1 paper, 2020). "Previous reports have shown that GDF-15 is also associated with cell apoptosis, senescence, and energy metabolic disorder due to mitochondrial dysfunction, which are hallmarks of aging." (PMID 32847145, 2020). "The secretary mechanism of GDF-15 may be associated with skeletal muscle dysfunction by physical inactivity, because the molecule is a footprint of an energy metabolic disorder due to mitochondrial dysfunction." (PMID 32847145, 2020). "They described that the GDF-15/GFRAL pathway regulates appetite and could be involved with energy metabolic disorder." (PMID 32847145, 2020).
enthesitis (1 paper, 2022). Inflammation at the site of insertion of ligaments, tendons, and other fibrous structures into bone. "- Relations of gender, smoking status and number of enthesitis with growth differentiation factor-15 (GDF-15) and EAT thickness of patients in the AxSpA group." (PMID 36104054, 2022). "The relationship between gender, smoking status, and the number of enthesitis with GDF-15 and EAT thickness values were not statistically significant." (PMID 36104054, 2022).
epilepsy (1 paper, 2022). A brain disorder characterized by episodes of abnormally increased neuronal discharge resulting in transient episodes of sensory or motor neurological dysfunction, or psychic dysfunction. "Serum GDF15 was elevated in 15 patients (upper limit 297.568 pg/ml), including 8 patients with epilepsy (8/15, 53%), 3 patients with myasthenia gravis (3/6, 50%), 3 patients with DMD (3/7, 42.9%), and 1 patient with viral encephalitis (1/2, 50%)." (PMID 35498801, 2022). "The results revealed that serum FGF21 and GDF15 levels were variably increased in the NMD group, especially in the patients with DMD and epilepsy." (PMID 35498801, 2022).